CXCL8 (C-X-C motif chemokine ligand 8)
Diseases named in the same sentence as CXCL8 in open-access papers (continued):
Sharing a sentence is not in itself a finding about the gene and the disease.
Cognitive impairment (54 papers, 2011 to 2026). Abnormal cognition is characterized by deficits in thinking, reasoning, or remembering. "Cognitive impairment in human cerebral malaria was associated with high cytokine levels in the cerebrospinal fluid (CSF) including IL-6, CXCL-8/IL-8, G-CSF, TNF-α and IL-1Ra, whereas a correlation between serum and CSF levels was only found for G-CSF." (PMID 28448579, 2017). "In this paper, we review the roles and regulatory mechanisms of pro-inflammatory chemokines (CCL2, CCL3, CCL4, CCL5, CCL11, CCL20, and CXCL8) in cognitive impairment." (PMID 39011039, 2024). "Likewise, CXCL8 (interleukin 8) has been found to be increased in both the serum and CSF of AD patients, as well as CXCL10 (IP-10), whose levels in CSF correlated with AD cognitive impairment." (PMID 31766244, 2019).
preeclampsia (54 papers, 2010 to 2025). Preeclampsia is a hypertensive disorder of pregnancy that is characterized by new-onset hypertension with proteinuria presenting after 20 weeks of gestation, and depending on mild or severe forms may initially present with severe headache, visual disturbances, and hyperreflexia. "The development of preeclampsia is associated with higher serum concentrations of CXCL8 (IL-8) and increased expression in placental tissue." (PMID 41463301, 2025). "The highest level of inflammation, associated with IL-6 and CXCL8, was observed in women with term labor compared to those with preeclampsia or preeclamptic syndrome." (PMID 41463301, 2025). "Implications of IL-6 and CXCL8 in pregnancy-associated pathological conditions, such as pregnancy loss, preeclampsia, gestational diabetes mellitus, and infection/inflammation have been reported." (PMID 37122732, 2023). "CXCL8 is a neutrophil chemoattractant upregulated in inflammatory reactions that has been implicated in the influx of maternal immune cells into the decidua during labor and in preeclampsia." (PMID 28717357, 2017). "Numerous studies have demonstrated that patients with severe preeclampsia exhibit elevated plasma levels of various chemokines—CXCL8 (IL-8), CCL2 (MCP-1), CXCL10 (IP10), and CXCL12 (SDF-1)—compared to healthy pregnant women." (PMID 41463301, 2025). "CXCL8 contributes to preeclampsia pathogenesis by recruiting neutrophils into vascular intima, where they release reactive oxygen species, myeloperoxidase, MMP-8, and thromboxane, causing cellular damage, endothelial inflammation, and vasoconstriction." (PMID 41463301, 2025). "CXCL8 has previously shown to be raised in placentas of participants with established preeclampsia, with exacerbations in severe disease." (PMID 39028417, 2024). "Moreover, Pinheiro and collaborators found that increased CXCL-8 positively correlated with increased IFN-γ in preeclampsia." (PMID 34925062, 2021). "When stratified, CXCL8 expression remained elevated in placentas obtained from FGR pregnancies, irrespective of concurrent preeclampsia (p = 0.0003 FGR, p = 0.0033 FGR/preeclampsia)." (PMID 39028417, 2024).
chorioamnionitis (53 papers, 2005 to 2025). A morphologic finding indicating inflammation of the fetal sac membranes. "The amnion secretes IL-1 during chorioamnionitis, which causes neutrophil accumulation via up-regulating the production of IL-8/CXCL8 and GCSF/CSF3." (PMID 37475854, 2023). "Decidual tissues from women with chorioamnionitis-induced preterm labor show substantial infiltration of maternal neutrophils recruited by decidual-derived chemokines like CXCL8." (PMID 41463301, 2025). "This notwithstanding, infants born in the context of chorioamnionitis or those with an unstable clinical course exhibited significantly lower CXCL8-producing CD4 and CD8 T cells when compared to stable infants." (PMID 32152273, 2020). "This chorioamnionitis‐induced immunosuppression includes the depletion of B and T lymphocytes in spleen, thymic involution, endotoxin hyporesponsiveness and lower CXCL8‐producing CD4 and CD8 T cells." (PMID 33006196, 2021). "Neutrophils specifically respond to the cytokine IL-8/CXCL8, which was found in decidua during chorioamnionitis." (PMID 37475854, 2023). "In this study, we show that babies born in the context of chorioamnionitis (inflammation) and those with repeated episodes of infection have lower CXCL8 responses but we do not know the mechanisms that link this association." (PMID 32152273, 2020).
liver fibrosis (52 papers, 2005 to 2025). "Chemokines CCL2 and CXCL8 have been shown to play critical roles for recruitment of inflammatory cells and their expression has been linked to liver fibrosis." (PMID 32933544, 2020). "Studies showed that CXCL8 promoted hepatic fibrosis by inducing α-smooth muscle actin (α-SMA) expression and stress fiber formation in HSCs." (PMID 37122694, 2023). "It has been reported that IL-6 and CXCL8 levels are related to the degree of liver fibrosis and can promote the process of liver fibrosis by inducing HSCs activation and regulating apoptosis." (PMID 35707473, 2022). "Since profibrogenic functions of HSCs are induced through CXCR2 and the CXCR2 ligand CXCL8 is associated with hepatic macrophage accumulation in human liver fibrosis, CXCR2 evolved as an attractive target for liver fibrosis treatment." (PMID 24646914, 2014). "Furthermore, among 24 evaluated cytokines, adipokines and osteokines, serum CXCL8, MCP-1, and osteopontin were independently associated with hepatic fibrosis in patients with biopsy-proven NAFLD." (PMID 40794228, 2025). "Then, module analysis of the 113 key OGEs was performed using MCODE and the CytoNCA plugin to obtain 6 core genes (CXCL8, MAPK1, AKT1, SRC, VEGFA, and IL-6), which might play important roles in the effects of JQH against WD-associated liver fibrosis." (PMID 35707473, 2022).
renal cell carcinoma (52 papers, 1998 to 2025). "A retrospective analysis of 1344 patients across four phase-3 clinical trials, encompassing patients receiving treatment for melanoma, NSCLC, and renal cell carcinoma found an association between serum CXCL8 levels and poor response to immune checkpoint inhibition." (PMID 34944914, 2021). "A study involving patients with melanoma, non-small cell lung cancer (NSCLC), and renal cell carcinoma (RCC) indicated that elevated baseline CXCL8 levels in plasma were linked to poorer clinical outcomes in patients receiving immunotherapy (such as nivolumab or ipilimumab)." (PMID 40573881, 2025). "In a study of urethral and renal cell carcinomas, both circulating CXCL8 protein and CXCL8 RNA were elevated in the peripheral blood monocular cells of patients who did not respond to PD‐1 checkpoint inhibitors." (PMID 35879507, 2022). "CXCL8 is an important contributor to sunitinib resistance, and CXCL8 blocking resensitizes renal cell carcinoma to sunitinib treatment." (PMID 35011369, 2021).
thyroid cancer (52 papers, 2014 to 2025). "Literature data, evidence that the specific genetic mutation harbored by thyroid cancer cells is related to a different ability to secrete CXCL8, which generally occurs at a higher level than NHT." (PMID 31741708, 2019). "The results of the present study show that the selective BRAF-inhibitor, PLX4720, inhibits the basal and the TNFα-stimulated secretion of CXCL8 in BRAFV600E mutated thyroid cancer cell lines (BCPAP, 8305C and 8505C)." (PMID 30867499, 2019). "Moreover, intratumoral levels of CXCL8 were significantly higher in patients with high-risk thyroid cancer compared with those with low-risk disease." (PMID 33986723, 2020). "The present study was specifically designed to test the possibility to inhibit the secretion of CXCL8 in thyroid cancer cells harboring specific genetic mutations and the characterization of the IFNγ signaling producing this inhibition appears by far behind the aim of our study." (PMID 27555670, 2016). "For example, CXCL8 was associated with better lymph node metastasis status in breast invasive carcinoma and head and neck squamous cell carcinoma, whereas the same chemokine was linked with worse lymph node metastasis status in esophageal carcinoma and thyroid carcinoma." (PMID 37686093, 2023). "It was recently shown that the inhibition of the secretion of CXCL8 by different pharmacological compounds reduces thyroid cancer cell migration in vitro." (PMID 38900374, 2025). "Previous studies have highlighted the significance of CXCL8 in thyroid cancer growth and progression." (PMID 38368303, 2024). "Third, TMC induce cancer cell stemness, showing enhanced stemness features when thyroid cancer cells are exposed to conditioned media by mast cells or when exposed to recombinant CXCL8/IL-8." (PMID 36293435, 2022). "Future studies specifically designed at clarifying the pathways involved in the different inhibitory effects of vitamin D on CCL2 and CXCL8 in thyroid cancer cells appear worthwhile." (PMID 35498406, 2022). "TAN recruited by CXCL8/IL-8 secrete GM-CSF and promote tumor cell survival and tumor progression, evidenced by research involving human thyroid cancer tissues that have shown correlation between TAN density and tumor size." (PMID 36293435, 2022). "Neutrophils are recruited by thyroid cancer cells by releasing CXCL8/IL-8 and granulocyte colony-stimulating factor." (PMID 34204889, 2021). "Some cytokines like CXCL8 (also known as interleukin-8 or neutrophil attractant/activation protein-1) are emerging as important players in the modulation of the thyroid cancer microenvironment, with a role for the initiation and maintenance of tumorigenesis." (PMID 32059434, 2020). "Bauerle and coworkers showed that CXCL8 was involved in thyroid tumor aggressiveness in an in vivo model of orthotopic thyroid cancer xenograft in nude mice." (PMID 33986723, 2020). "The importance of CXCL8 in the growth and progression of thyroid cancer has been demonstrated by several studies." (PMID 33986723, 2020). "MCs were reported to induce EMT and cancer stem cell signatures in human thyroid cancer through CXCL8/IL-8 pathways." (PMID 32625213, 2020). "In particular, among thyroid cancer cells harboring different oncogenic mutations, those bearing the BRAF V600E mutation secrete the highest amounts of CXCL8." (PMID 31762942, 2019). "The results of the present study constitute the first demonstration of a CXCL8-inhibiting effect exerted by PLX4720 in thyroid cancer cells and should be regarded as potentially relevant." (PMID 30867499, 2019). "As a matter of fact, targeting the receptors for CXCL8 proved to have therapeutic benefits in experimental models of thyroid cancer." (PMID 31741708, 2019). "CXCL8 is a chemokine secreted by normal and thyroid cancer cells with proven tumor-promoting effects." (PMID 30867499, 2019).
thyroid cancer (continued). "CXCL8 favors tumor progression by promoting the metastatic spread of thyroid cancer through the induction of epithelial to mesenchymal transition." (PMID 31741708, 2019). "Experimental evidence demonstrates that thyroid cancer cells produce larger amounts of CXCL8 as compared with normal thyroid cells." (PMID 31762942, 2019). "Aim of the present study was to investigate the potential anti-cancer effect of phenformin in terms of cell viability and modulation of CXCL8 secretion in normal and thyroid cancer cells." (PMID 31741708, 2019). "In this scenario, no previous study investigated the role of BRAFV600E oncogene in influencing the production of CXCL8 within thyroid cancer microenvironment." (PMID 30867499, 2019). "Experimental data from previous in vitro and in vivo studies indicate that CXCL8 is responsible for a more aggressive clinical course of differentiated thyroid cancer." (PMID 31741708, 2019). "With specific regard to thyroid cancer, metformin was found to reduce cell proliferation, to inhibit the secretion of the pro-tumorigenic chemokine CXCL8, and to induce thyroid cancer cell death." (PMID 31741708, 2019). "Aim of this study was to test the effect of the BRAF-inhibitor (PLX4720) on the basal and TNF-α-induced CXCL8 secretions in BRAFV600E mutated (BCPAP, 8305C, 8505C), in RET/PTC rearranged (TPC-1) thyroid-cancer-cell-lines and in normal-human-thyrocytes (NHT)." (PMID 30867499, 2019). "Several agents were previously reported to have an inhibiting effect on the secretion of CXCL8 in thyroid cancer microenvironment." (PMID 31741708, 2019). "With specific regards to thyroid cancer, CXCL8 was the first chemokine shown to be secreted by normal human thyroid cells." (PMID 31762942, 2019). "Initially, it was believed that the expression of CXCL8 mRNA in different thyroid cancer cell lines was mainly regulated by NF-κB." (PMID 29977225, 2018). "Studies taking into account the role of CCL15, C–X–C motif ligand 12, CXCL16, CXCL1, CCL20, and CCL2 in the context of thyroid cancer will be reviewed with particular emphasis on CXCL8." (PMID 29977225, 2018). "CXCL8 favors tumor progression through several mechanisms, which include the promotion of thyroid cancer metastatic spread and EMT." (PMID 29977225, 2018). "The main concept emerging from these in vitro data is that the type of oncogenic lesion harbored by thyroid cancer cells accounts for their different ability to secrete CXCL8." (PMID 29977225, 2018). "Moving to in vivo experiences, the involvement of CXCL8 in the metastatic process of thyroid cancer cells was studied in NOD/SCID mice transfected with a thyroid cancer cell line." (PMID 29977225, 2018). "Solid evidence from in vitro and in vivo studies supports a major role for CXCL8 in determining a more aggressive clinical course of differentiated thyroid cancer." (PMID 29977225, 2018). "Subsequently, it was found that, besides KHM-5M cells, neoplastic cells derived from other types of thyroid cancer secrete CXCL8, which is involved in thyroid cancer-related inflammation." (PMID 29977225, 2018). "Immune depletion experiments not only identified CXCL8 as the most powerful inducer of EMT but also provided evidence that the presence of CXCL8 is a necessary condition for inducing EMT in thyroid cancer cells." (PMID 29977225, 2018). "While solid evidence already indicated that thyroid cancer cells secrete CXCL8, the role of this chemokine in influencing the biological behavior of thyroid cancer and more specifically its pro-tumorigenic effect had to be established." (PMID 29977225, 2018). "At present, a widely addressed topic regards the ability of CXCL8 to promote the metastatic spread of thyroid cancer cells." (PMID 29977225, 2018). "At present, CXCL8, in view of its proven pro-tumorigenic effects, is the most extensively investigated chemokine involved in thyroid cancer." (PMID 29977225, 2018).
thyroid cancer (continued). "It has been also shown that histamine and chemokines (CXCL1/GRO-α, CXCL10/IP-10, and CXCL8/IL-8) released by activated human MCs modulate proliferation, survival, and invasion of thyroid cancer cells through the involvement of specific receptors." (PMID 27732965, 2016). "This different ability of metformin to inhibit the secretion of CXCL8 suggested that in normal thyrocytes and thyroid cancer cell lines bear different secretory pathways of CXCL8 which would imply that specific inhibitory strategies are required." (PMID 27555670, 2016). "Thus, the present in vitro study aims to investigate the therapeutic effects of AZD5069 in differentiated thyroid cancers in terms of thyroid cancer cell viability, proliferation, CXCL8 secretion and cell migration." (PMID 38900374, 2025). "This study aimed to evaluate if the targeting of CXCR2 by its selective antagonist, AZD5069, could modulate CXCL8-mediated pro-tumorigenic effects in thyroid-cancer (TC) cells in vitro." (PMID 38900374, 2025). "Regarding mast cells in tumors, a previous study showed that the presence of mast cells in ATC correlates with tumor aggressiveness and that mast cells induce epithelial-mesenchymal transition in thyroid cancer cell lines, mainly by activating CXCL8 in the AKT/SLUG pathway." (PMID 35222534, 2022). "CXCL8 is the most studied pro-tumorigenic chemokine promoting cancer progression, angiogenesis, and metastasis, whose role was recently deeply investigated also in thyroid cancer." (PMID 35498406, 2022). "CCL2 and CXCL8 concentrations were assayed in the supernatants of 8505C thyroid cancer cell lines." (PMID 35498406, 2022). "CCL2 and CXCL8 concentrations were assayed in the supernatants of TPC-1 thyroid cancer cell lines." (PMID 35498406, 2022). "Furthermore, vitamin D differently modulates the secretion of CCL2 and CXCL8 by thyroid cancer cell lines." (PMID 35498406, 2022). "Therefore, the mast cells-dependent CXCL8/IL-8-Akt-Slug pathway can be considered as a target in the development of treatment modalities for thyroid cancer." (PMID 32626535, 2020). "Furthermore, thyroid cancer cell lines were able to promote neutrophil recruitment and survival through CXCL8 and GM-CSF (granulocyte macrophage-colony stimulating factor), respectively." (PMID 33986723, 2020). "A recent study by our group showed that the BRAF-inhibitor PLX4720 reduced CXCL8 secretion in several BRAFV600E mutated thyroid cancer cell lines (8505C, 8305C, BCPAP), but not in RET/PTC rearranged ones (TPC1)." (PMID 31762942, 2019). "Furthermore targeting/lowering of CXCL8 levels is known to produce beneficial effects in thyroid cancer." (PMID 30867499, 2019). "Whether this BRAF-inhibitor also exerts a CXCL8-lowering effect,in thyroid cancer cells remains to be investigated." (PMID 30867499, 2019). "Thus, lowering CXCL8 concentrations in thyroid cancer microenvironment requires specific strategies depending on the specific oncogenic background of neoplastic cells." (PMID 30867499, 2019). "Aim of the present study was to test the effect of PLX4720 on the secretion of CXCL8 in normal human thyroid (NHT) cells, in the BCPAP, 8305C and 8505C thyroid cancer cell line harboring the BRAF V600e mutation and in the TPC-1 thyroid cancer cell line bearing the RET/PTC re-arrangement." (PMID 30867499, 2019). "Thus, the composition of thyroid cancer microenvironment, and in particular the levels of CXCL8 are currently regarded as a key factor for driving tumor progression." (PMID 30867499, 2019). "Importantly, PLX4720 was able to reduce the migration of thyroid cancer cells, but this effect occurred only in those cells in which PLX4720 also inhibited the secretion of CXCL8 (the BRAF V600E mutated ones)." (PMID 31762942, 2019). "The modality of CXCL8 secretion by thyroid cancer cells was investigated in several studies." (PMID 29977225, 2018).